INS (insulin)
Diseases named in the same sentence as INS in open-access papers (continued):
Sharing a sentence is not in itself a finding about the gene and the disease.
diabetes (continued). "The toxicity issue is important, especially in the case of future implantable immunosensors, which might serve, e.g., the in vivo monitoring of insulin along with glucose in patients with various types of diabetes." (PMID 37571553, 2023). "Considering the four patients with diabetes mellitus, 50% (n = 2) were in nutritional therapy, one patient was treated by metformin and basal glargine insulin, and one patient was treated with multiple daily insulin injections." (PMID 37829686, 2023). "We performed functional protein analyses such as transactivation, protein expression, DNA binding, nuclear localization, and glucose stimulated insulin secretion (GSIS) assay, along with structural prediction analysis for 14 HNF1A variants found in 20 patients with monogenic diabetes." (PMID 37396188, 2023). "Future studies might also examine the effects of other diabetes medications such as metformin on nicotine intake in insulin resistant rats." (PMID 38389818, 2023). "For people with (pre)diabetes, a KD reduced glycosylated hemoglobin (HbA1C), fasting glucose, fasting insulin, weight, blood pressure, triglycerides, alanine aminotransferase, and high-density lipoprotein, consistent with safety and tolerability for long-term adherence." (PMID 36937529, 2023). "Furthermore, the protective activity of MMP-2 against β-cell death ameliorated hyperglycemia and enhanced insulin secretion and islet β-cell mass in an experimental animal model of diabetes mellitus." (PMID 37047672, 2023). "In summary, the application of cMDSCs propagated from GM-CSF, IL-6, and IL-1β cytokines can improve renal function and increase insulin secretion from pancreatic islets, thereby prolonging the diabetes-free survival of NOD–SCID mice after treatment with T cells." (PMID 37296628, 2023). "Consistently, serum Pdia4 was shown to be related to obesity, insulin sensitivity, and diabetes." (PMID 36935456, 2023). "Insulin injections are stressful but necessary for people with diabetes." (PMID 37474582, 2023). "Insulin mimetics with agonistic or antagonistic effects toward the receptor are an exciting field of research and could find applications in treating diabetes or malignant diseases." (PMID 36633503, 2023). "Second, unmeasured confounding might have occurred because data on some potential confounders such as diet, duration of diabetes, use of insulin, type of antidiabetic drugs, and medication adherence were not available." (PMID 38093333, 2023). "In addition, measures of glucose and insulin would be useful to further explore metabolic responses, and testing in populations with diabetes is warranted." (PMID 36305961, 2023). "Through this study, we suggested the possibility that high mitophagy activity by mitochondria ROS may play a key role in the development of diabetes through the inhibition of beta cell growth and decreased insulin secretion." (PMID 37134105, 2023). "• Glucose uptake and TCA cycle flux decreased, mitochondria was fewer in insulin-resistant offspring skeletal muscle of diabetes history. • O-GDM had decreased PPARGC1A in skeletal muscle. • Fatty acid flux into myotube and LPL expression were lower in offspring of T2DM parents." (PMID 37255932, 2023). "Examining histological and biochemical data, the high dose of S. costus prepared from a botanical source showed potential for treating diabetes and other complications attributed to ameliorating body weight, lipid profile, oxidative stress, insulin, and glucose levels." (PMID 37367922, 2023). "It is established that streptozocin (STZ) infiltrates the pancreas and invades insulin synthesizing β-cells that subsequently leads to diabetes mellitus (DM) induction evidenced by hypoinsulinemia and hyperglycemia within a week after its administration in the experimental animal models." (PMID 37888717, 2023).
diabetes (continued). "Our correlation analysis indicated that diabetes statuses, such as glucose control, insulin levels, and insulin resistance, may be potential factors affecting T2DM brain damage to the right ARC." (PMID 36112176, 2023). "In terms of “double diabetes”, there is evidence to suggest that fasting can improve both insulin sensitivity and glucose metabolism, which may have beneficial effects on individuals with “double diabetes”." (PMID 37630716, 2023). "We confirmed that AH supplementation can effectively control blood glucose and insulin levels by improving insulin sensitivity and may be a potential agent for glycemic control in subjects with prediabetes and type 2 diabetes mellitus." (PMID 37895834, 2023). "This cross-sectional study seeks to address this knowledge gap by examining the behavioral intentions (BIs) of wearable insulin biosensors among diabetes patients, the factors that drive or hinder their usage, and the implications for diabetes management and healthcare outcomes." (PMID 38239544, 2023). "In future work, targeting abnormal cerebral glucose metabolism, such as improving brain insulin resistance, may be a promising strategy for improving diabetic cognitive dysfunction." (PMID 37396164, 2023). "Hyperglycemia and impaired insulin action are the main hallmarks of diabetes." (PMID 38203600, 2023). "In turn, insulin preparations with improved properties, in particular, more stable during long-term storage and with fewer side effects, will be used in the treatment of insulin-dependent diabetes mellitus." (PMID 36835194, 2023). "The TXNIP gene encodes for the thioredoxin interacting protein, which is primarily involved in inflammatory, metabolic and apoptotic processes, and plays an important role in the development of diabetes, by influencing insulin production and beta-cell apoptosis." (PMID 36791658, 2023). "One possible explanation for this finding is that patients in our sample who received insulin might have had better control of their diabetes." (PMID 39035064, 2023). "Following the inhibition of insulin secretion by the increased serum values of somatostatin, patients with somatostatinoma can present hyperglycemic changes through glucose intolerance from modified fasting glucose to the onset of diabetes." (PMID 37628857, 2023). "It was suggested that BCAA excess might be a predictive factor of the development of IR and type 2 diabetes mellitus, and it might promote IR by interference with insulin signaling in muscles." (PMID 36672616, 2023). "Participants’ expert critiques identified structures within the New Zealand health system precluding equal access to diabetes technologies outside of the trial; namely insulin pump access criteria and healthcare professionals influencing technology advocacy and support." (PMID 37250371, 2023). "Retinal microvascularization was altered in patients with type 1 diabetes without clinical signs of diabetic retinopathy, but intensive insulin treatment and optimized diabetes management with continuous glucose-monitoring devices seemed to attenuate the risk of retinal vascular density rarefaction." (PMID 37048770, 2023). "Similarly, with SHAP, DT and KNN resulted in the highest AUC of 0.77 with associated risk factors, such as systolic blood pressure, history of hypertension, diabetes mellitus duration, insulin treatment, fasting plasma glucose, and glycosylated hemoglobin." (PMID 37370980, 2023). "STS and EURO Scores take into account risk factors that may influence the incidence of these complications (presence of COPD, diabetes on insulin, peripheral/central arterial disease, etc.)." (PMID 37004541, 2023). "The upregulation of inflammatory cytokines by iron was considered above (Section 5.2), but given the protean effects of activating inflammation pathways on insulin signaling and other diabetes-related pathways, those findings likely represent the tip of the iceberg." (PMID 36137277, 2023).
diabetes (continued). "Pregestational diabetes dominated (31/47; 60%), with 47% having T1D and 94% requiring insulin." (PMID 38047210, 2023). "However, DCM-HFpEF patients had a longer diabetes duration, a higher proportion of PH and were more likely to be treated with insulin and hemodialysis." (PMID 36836101, 2023). "In addition, the outcome of this study suggests that measurement of blood insulin levels should be included in mandatory medical certification examinations, along with glucose levels, to counteract the development of diabetes." (PMID 37887427, 2023). "Consequently, both types of diabetes result in ineffective blood glucose regulation due to insufficient insulin activity." (PMID 38203517, 2023). "However, exosomal miRNAs and lncRNAs have been shown to play a role in modulating the progression of diabetes, including affecting metabolic and insulin signals in target tissues, cell viability, and pancreatic cell inflammation." (PMID 36818396, 2023). "Therapy that specifically depletes anti-insulin B cells reduces diabetes development in NOD mice." (PMID 37261716, 2023). "Insulin and its biosimilars are indispensable for patients with diabetes." (PMID 37077814, 2023). "In univariate regression models, time (hour of the day and hour-squared, both (p < 0.001), younger age (p=0.001), shorter duration of diabetes (p < 0.001), lower insulin dose per kilogram (p < 0.001), and lower hemoglobin A1c (p < 0.001) were associated with higher TIR." (PMID 37929231, 2023). "Current treatments for diabetes include insulin secretagogues, biguanides, insulin sensitizers, alpha-glucosidase inhibitors, incretin mimetics, amylin antagonists, and sodium-glucose co-transporter-2 (SGLT2) inhibitors, glucagon-like peptide-1 (GLP-1) receptors agonists." (PMID 38273819, 2023). "The resulting deterioration in insulin secretion and action may lead to the development of diabetes or acceleration of the transition from a pre-diabetic phase to diabetes." (PMID 38074488, 2023). "The initiation of insulin therapy in T2D can be relatively straightforward, but the need for a timely follow-up to assure an optimal titration is a challenge, not only for subjects with diabetes but also for healthcare professionals and healthcare systems." (PMID 37835008, 2023). "Here, we report results from the Assessing Non‐adjunctive CGM Safety at Home and In New Markets (ANSHIN) study that evaluated the impact of non‐adjunctive use of this CGM system on glycaemic control in adults with intensive insulin therapy (IIT)‐managed diabetes." (PMID 36864014, 2023). "Therefore, they are extensively scrutinized for their effects on metabolism, steroidogenesis, insulin signaling, and inflammation involving obesity, diabetes, and the reproductive system." (PMID 37854189, 2023). "Previous investigations have exhibited that the intake of L-arginine can improve endothelial function, insulin secretion and sensitivity, and inflammation, all of which are interconnected with obesity-induced ailments such as type 2 diabetes mellitus and cardiovascular diseases." (PMID 37623843, 2023). "Knowledge about the role of β-cell subpopulations will also be useful when developing new treatments, such as identifying and preserving functional subpopulations in diabetes and generating stem cell-derived insulin-secreting cells for restoring insulin secretion." (PMID 38018905, 2023). "However, outside of pregnancy, it is common practice for adults with diabetes to self-manage insulin administration during medical procedures, such as short surgeries." (PMID 37131168, 2023). "In diabetes, a reduction of the cellular capacity to efficiently respond to insulin stimulation, together with impaired insulin secretion and action, may explain many alterations of the mitochondrial function." (PMID 36672627, 2023). "Continuous Glucose Monitoring (CGM) is a key tool for insulin-treated people with diabetes (PwD)." (PMID 37676398, 2023).
diabetes (continued). "From a translational point of view, the reconstituted antiviral immunity induced by insulin-driven correction of hyperglycaemia highlights the importance of a meticulous and proactive tight glucose control strategy in diabetics, including during acute infection." (PMID 38093014, 2023). "Furthermore, our study introduces the finding that in human AT, DVL2 expression is influenced by both fat depot, diabetes, sex, and obesity, aligning with previous research linking this gene to insulin sensitivity." (PMID 38139277, 2023). "Furthermore, SGLT2 inhibitors also reduce hyperglycemia-induced glucotoxicity, which refers to the ability of excess glucose to impair both insulin secretion and insulin action, leading to a vicious cycle of worsening glycemic control in diabetes mellitus." (PMID 37111578, 2023). "In conclusion, urinary insulin signaling pathway related proteins may be potential biomarkers for monitoring diabetes." (PMID 36749274, 2023). "This leads to poor planning and resource allocation to diabetes programmes – such as an inability to quantify demand for insulin and diabetes supplies – and results in poor quality care for diabetes patients, as well as exacerbating common comorbidities such as HIV and tuberculosis." (PMID 36692486, 2023). "Our studies have shown that a combination of IP6 and inositol provides a synergistic effect in the treatment of diabetes by attenuating several factors such as total cholesterol, triglycerides, intestinal amylase activity and food and fluid intake, and insulin sensitivity." (PMID 37371552, 2023). "Therefore, increasing the number of insulin-producing beta cells while decreasing the number of glucagon-producing alpha cells turns out to be a promising therapeutic avenue in diabetes treatment." (PMID 37008919, 2023). "A higher resting HR in individuals without diabetes mellitus is associated with future unfavorable changes in insulin levels and insulin sensitivity." (PMID 36991469, 2023). "According to the recommendations of the American Diabetes Association, insulin treatment should be given if HbA1c does not reach the appropriate target despite the use of two or more oral hypoglycemic agents." (PMID 36831436, 2023). "Type 1 diabetes mellitus (T1DM), juvenile diabetes, or insulin-dependent diabetes, is an autoimmune disease that leads to the destruction of insulin-producing pancreatic beta cells, causing an absolute deficiency of insulin." (PMID 36982244, 2023). "Insulin was used to treat 37.3% of patients diagnosed with diabetes at the time of admission." (PMID 36755914, 2023). "The published data showed that in non-diabetes population the plasma insulin level reached the peak (> 10 times of fasting value) at about 1 h after intake of a mixed-meal containing 50 g of carbohydrates, and kept at 2–4 times of fasting value at 2-3 h after intake." (PMID 36782111, 2023). "Furthermore, the D and SD groups had relatively higher values of diabetes-related blood parameters (insulin, HOMA-IR, TyG Index, FPG, and HbA1c), compared with the S and NSND groups." (PMID 38068813, 2023). "Therefore, strategies to contain diabetes among undernourished populations should focus on the restoration of insulin sensitivity as we cannot improve insulin secretion due to fetal programming." (PMID 37601212, 2023). "This could perhaps be due to STZ-induced toxicity, hyperglycemia/diabetes, or impaired insulin signaling in the hippocampus." (PMID 37443762, 2023). "Human hsa-miR-375 is involved in the regulation of insulin secretion and it has been suggested that it may therefore be a new pharmacological target for the treatment of diabetes mellitus." (PMID 36859746, 2023). "Diabetes mellitus is a serious, chronic disease that arises when blood glucose levels rise due to the body's inability to secrete any or enough of the hormone insulin or to use the insulin efficiently as it does." (PMID 37809188, 2023).
diabetes (continued). "Disturbance in IR internalization leads to hyperinsulinemia by prolonging insulin half-life in the circulation, a process that may also be disrupted in insulin-resistant obese individuals and patients with type 2 diabetes mellitus." (PMID 36548088, 2023). "Furthermore, the UK Prospective Diabetes Study (UKPDS) demonstrated that early insulin therapy in T2DM patients reduces macrovascular complications." (PMID 37264625, 2023). "In these cases, in addition to heating, it is therefore also necessary to treat the concomitant pathologies: administer insulin for hyperglycemia in diabetes, glucose for hypoglycemia, cortisone for acute adrenal insufficiency or broad-spectrum antibiotic therapy for sepsis." (PMID 38138917, 2023). "Additionally, SGLT2 inhibitors can modify adipocytes and their production of cytokines, such as adipokines and adiponectin, which enhances insulin sensitivity and delays diabetes onset." (PMID 37047011, 2023). "However, functional defects in insulin secretion occur over time and then type 2 diabetes mellitus arises." (PMID 37147652, 2023). "Diabetes mellitus is a metabolic disease that can be caused by the pancreas not being able to produce enough insulin or the body not being able to use this insulin effectively and is, therefore, characterized by higher-than-normal blood glucose ranges." (PMID 37394885, 2023). "However, most individuals with diabetes have type II diabetes, which is typically characterized by insulin resistance in peripheral tissues and a reduction in insulin responsiveness." (PMID 37373340, 2023). "Therefore, we evaluated the synergic effect of our synbiotic combinations on mammalian glucose homeostasis and insulin sensitivity in C57BL/6J mice with diabetes and diet-induced obesity." (PMID 37584728, 2023). "In addition, excessive activation of JNK-1 in islet cells can lead to insufficient insulin secretion and apoptosis of islet cells, thus leading to diabetes." (PMID 38075030, 2023). "Remarkably, a century later, insulin remains a cornerstone of diabetes treatment." (PMID 36845885, 2023). "Amongst patients with diabetes, the most common diabetes medications were insulin and insulin analogs (53.7%), biguanides (40.8%), and sulfonylureas (22.3%); use of sodium–glucose co-transporter inhibitors (3.2%) and glucagon-like peptide-1 receptor agonists (1.1%) was less common." (PMID 37592272, 2023). "When exenatide was added to optimized basal insulin, improvements in glycemic control and weight loss were observed regardless of baseline A1C, diabetes duration or BMI." (PMID 37589043, 2023). "The pattern of these lipid subclass alterations was up-regulation in obese people, down-regulation in diabetics, and then up-regulation as an effect of metformin, reaffirming the role of metformin in enhancing insulin sensitivity and glucose uptake by cells and in regulating lipid metabolism." (PMID 38139843, 2023). "Many monogenic diabetes subtypes may respond to therapies other than insulin and have chronic diabetes complication prognosis that is different from T1D." (PMID 36178555, 2023). "Since HOMA-IR is commonly affected by exogenous insulin injection in diabetes patients, we believed that TyG-BMI could replace other IR indexes in clinical settings as an effective one to evaluate the testosterone decrease or deficiency." (PMID 37361537, 2023). "In addition to a positive reflection in insulin sensitivity indicating good control of diabetes among study participants, the level of HbA1C showed a reduction from 6.1 to 5.9 at the first follow-up." (PMID 38022144, 2023). "However, the specific mechanism of insulin secretion regulation is still a hot spot pursued by diabetes researchers worldwide." (PMID 37255814, 2023).